AURKA (aurora kinase A)
Diseases named in the same sentence as AURKA in open-access papers (continued):
Sharing a sentence is not in itself a finding about the gene and the disease.
renal fibrosis (3 papers, 2023 to 2025). A final common manifestation of a wide variety of chronic kidney diseases characterized by glomerulosclerosis and tubulointerstitial fibrosis. "The role of AURKA in fibrotic diseases has been less reported, but studies have shown that AURKA plays an important role in alcoholic liver fibrosis, renal fibrosis and myofibrosis." (PMID 39834933, 2024). "Recent studies have shown that inhibition of AURKA can reduce renal fibrosis in patients with chronic kidney disease." (PMID 36778123, 2023). "Aurora kinase A (AURKA) has been implicated in promoting myeloid and renal fibrosis." (PMID 39834933, 2024).
rhabdomyosarcoma (3 papers, 2012 to 2025). A rare aggressive malignant mesenchymal neoplasm arising from skeletal muscle. "When AURKA inhibitor alisertib is combined with navitoclax (a Bcl2 inhibitor) in experiments involving fusion-positive rhabdomyosarcoma cell lines and patient-derived xenografts, a potent synergy emerges." (PMID 39802403, 2025).
systemic mastocytosis (3 papers, 2022 to 2025). Systemic mastocytosis (SM) comprises a heterogeneous group of rare acquired and chronic hematological malignancies that are related to an abnormal proliferation of mast cells in tissue, including bone marrow, with or without skin involvement. "It is well known that Aurora kinase A (AKA) over-expression promotes tumorigenesis, but its role in the pathogenesis of systemic mastocytosis (SM) has not yet been investigated." (PMID 35159005, 2022).
urothelial cell carcinoma (3 papers, 2017 to 2021). "AURKA SNPs reduce the risk of large tumors in patients with hepatocellular carcinoma and are protective factors against urothelial cell carcinoma." (PMID 33050100, 2020). "In addition, AURKA polymorphism may influence the prognosis of cancer because the presence of certain AURKA SNPs is associated with longer progression-free survival for advanced urothelial cell carcinoma or other solid tumors." (PMID 33050100, 2020). "AURKA was reported to act a pivotal part in abrogating G2 checkpoint induced by DNA damage in urothelial cell carcinoma." (PMID 34336648, 2021).
asthma (2 papers, 2017 to 2023). "Conversely, pathways such as arachidonic acid metabolism, linoleic acid metabolism, and asthma displayed a positive association with AURKA expression." (PMID 37965456, 2023). "We identified disease specific dysregulation of the histone kinase AURKA in AECs, which may play a role in processes important in the pathogenesis of asthma such as proliferation and inflammation." (PMID 28137284, 2017). "Given that AECs from asthmatics are mitotically dyssynchronous, show defects in cell cycle regulation, and exhibit abnormal proliferation and delayed wound repair, our finding of increased AURKA expression may indicate aberrant regulation of these processes in asthma." (PMID 28137284, 2017).
astrocytoma (2 papers, 2017 to 2019). "We found that high SIX3 expression in astrocytoma resulted in low sensitivity to aurora kinase inhibitors, and this may partially be due to low expression of AURKA and AURKB." (PMID 28595628, 2017). "The expression of SIX3, AURKA, and AURKB were further studied in 18 human astrocytoma samples, and both AURKA and AURKB expression showed an inverse relationship with the expression of SIX3." (PMID 28595628, 2017). "A strong inverse correlation between SIX3 and AURKA/AURKB were obtained with normal astrocyte cell line HEB and three astrocytoma cell lines by Western blotting." (PMID 28595628, 2017). "SIX3 is a novel negative transcriptional regulator and acts as a tumor suppressor that directly represses the transcription of AURKA and AURKB in astrocytoma." (PMID 28595628, 2017). "Three primary human patient-derived astrocytoma lines were cultured, and the expression of SIX3, AURKA, and AURKB was examined." (PMID 28595628, 2017). "SIX3 silencing results in high expression of AURKA and AURKB in astrocytoma." (PMID 28595628, 2017). "SIX3 is identified as a novel negative transcriptional regulator of AURKA and AURKB, and it decreases the expression of AURKA and AURKB in a dose-dependent manner in astrocytoma cells." (PMID 28595628, 2017). "We demonstrate that in astrocytoma, SIX3 acts as a tumor suppressor gene by transcriptionally repressing AURKA and AURKB but does not affect the interaction of AURKA and AURKB." (PMID 28595628, 2017). "Since SIX3 has been confirmed as a negative transcriptional regulator of AURKA and AURKB, we wondered whether SIX3 expression is correlated with the sensitivity of astrocytoma cells to aurora kinase inhibitors." (PMID 28595628, 2017).
brain cancer (2 papers, 2024). A primary or metastatic malignant neoplasm affecting the brain. "Aurora kinase A (AURKA) has been implicated in GBM progression and is a potential therapeutic target for this aggressive brain cancer." (PMID 38774408, 2024). "Our research identifies AURKA as a key regulator of the immune response in GBM models, highlighting the potential for targeting this kinase in conjunction with immune-based therapies as a promising combination treatment strategy for this highly aggressive and difficult-to-treat brain cancer." (PMID 38995006, 2024).
carcinoma in situ (2 papers, 2010 to 2011). "In carcinoma in situ of TGCTs the spindle checkpoint proteins MAD2 and BUB1B are significantly less expressed compared to normal testis, while the expression of AURKA is increased." (PMID 20411023, 2010). "There was a significantly lower expression of the spindle checkpoint proteins in carcinoma in situ compared to normal testis (P=0.008 and P=0.043 for BUB1B and MAD2, respectively), while the level of AURKA was increased, however, not significantly (P=0.18)." (PMID 20411023, 2010).
carcinosarcoma (2 papers, 2020 to 2025). A malignant tumor composed of a mixture of carcinomatous and sarcomatous elements. "BLM, AURKA and PITX1 were upregulated in each subtype and were more significantly upregulated in carcinosarcoma tumours than endometrioid." (PMID 32899298, 2020).
chordoma (2 papers, 2022 to 2023). Chordomas are rare malignant tumors arising from embryonic remnants of the notochord in axial skeleton. "Significant differences between chordoma and normal tissue were identified for three kinases: Aurora kinase A (AURA), Cyclin-dependent kinase 9 (CDK9) and MAPK/MAK/MRK overlapping kinase (MOK)." (PMID 37197427, 2023).
Cirrhosis (2 papers, 2019 to 2024). A chronic disorder of the liver in which liver tissue becomes scarred and is partially replaced by regenerative nodules and fibrotic tissue resulting in loss of liver function. "Because 90% of HCC cases have a natural history of unresolved inflammation and severe fibrosis (or cirrhosis), we then examined the fibrosis marker genes, including collagen type I alpha 1 (cola1a1), connective tissue growth factor (ctgfa), and heparanase (hpse) in the AURKA transgenic fish." (PMID 31269749, 2019).
clear cell ovarian carcinoma (2 papers, 2010 to 2023). "Despite ENMD- 2076 did not meet the efficacy bar set in this trial, this AURKA inhibitor has been reported as potentially advantageous for ovarian clear cell carcinomas patients with ARID1A deficiency." (PMID 36890819, 2023). "Finally, a phase 2 clinical trial to assess the activity of a strong selective inhibitor for AURKA, ENMD- 2076, in treating patients with ovarian clear cell carcinomas was recently concluded (NCT01914510)." (PMID 36890819, 2023).
cutaneous melanoma (2 papers, 2016 to 2024). A primary melanoma arising from atypical melanocytes in the skin. "In addition, in skin cutaneous melanoma, AURKA can inhibit the infiltration of CD8+ T cells and promote hypoxia by activating the TGF-β signaling pathway." (PMID 39314848, 2024).
diffuse large B-cell lymphoma (2 papers, 2021 to 2025). "The integration of an AURKA inhibitor in conjunction with chidamide constitutes a novel and potentially effective therapeutic approach for the treatment of relapsed or refractory diffuse large B-cell lymphoma (DLBCL)." (PMID 40426926, 2025).
diffuse midline glioma (2 papers, 2024). A diffuse glioma that arises from the midline structures of the central nervous system. "Other groups have also demonstrated a synergistic effect of simultaneously blocking AURKA and PLK-1 in preliminary studies in diffuse midline glioma, paving the way for this promising combinatorial strategy to be translated into clinical trials." (PMID 39684470, 2024).
endometrioid adenocarcinoma (2 papers, 2015 to 2025). An adenocarcinoma characterized by the presence of malignant glandular epithelial cells resembling endometrial cells. "In this study we showed that overexpression of AURKA was significantly higher in non-endometrioid adenocarcinoma and in grade 3 tumors that are classified Type II tumors." (PMID 25625960, 2015).
Joubert syndrome (2 papers, 2024 to 2025). Joubert syndrome (JS) is characterized by congenital malformation of the brainstem and agenesis or hypoplasia of the cerebellar vermis leading to an abnormal respiratory pattern, nystagmus, hypotonia, ataxia, and delay in achieving motor milestones. "To understand AURKA’s role in regulating renal cyst development we conditionally deleted the gene in mouse models of Autosomal Dominant PKD (ADPKD) and Joubert Syndrome, caused by Polycystin 1 (Pkd1) and Inositol polyphosphate-5-phosphatase E (Inpp5e) mutations respectively." (PMID 38191531, 2024).
liver disease (2 papers, 2018 to 2025). "Furthermore, AURKA is implicated in cell cycle regulation and epigenetic modifications, illustrating the complex regulatory roles of AURKA in liver disease development." (PMID 40746357, 2025). "AURKA is also significantly involved in epigenetic regulation and liver diseases." (PMID 40746357, 2025).
medullary thyroid cancer (2 papers, 2019 to 2024). "Given these premises on PTTG1 and AURKA involvement in thyroid tumorigenesis, we decided to explore their association and their prognostic significance in a large cohort of sporadic medullary thyroid cancer samples." (PMID 30911297, 2019).
metastatic colorectal cancer (2 papers, 2012 to 2015). "Increased Aurora kinase A gene copy number (AURKA-CN) has been reported in metastatic colorectal cancer (mCRC), with unknown relationship to clinical outcome." (PMID 22240781, 2012).
metastatic melanoma (2 papers, 2016 to 2021). A melanoma that has spread from its primary site to another anatomic site. "Increased expression levels of AURKA or AURKB are significantly correlated with poor patient survival in metastatic melanoma patients." (PMID 33123754, 2021). "Furthermore, AURKA was expressed at a significantly higher level in tumor samples from metastatic melanoma patients who did not respond to TIL ACT compared with those who responded (p = 0.042)." (PMID 33123754, 2021).
Pan (2 papers, 2021 to 2025). "Pan-carcinoma differential expression analysis of AURKA also demonstrates that it is highly expressed across a wide spectrum of tumor types." (PMID 41471272, 2025).
peripheral T-cell lymphoma (2 papers, 2024 to 2025). "Alisertib targets AURKA by disrupting mitotic spindle formation and is being investigated for treating peripheral T-cell lymphoma." (PMID 39596419, 2024).
polycystic kidney disease (2 papers, 2024 to 2025). A usually autosomal dominant and less frequently autosomal recessive genetic disorder characterized by the presence of numerous cysts in the kidneys leading to end-stage renal failure. "Finally, dexamethasone reduces Aurora kinase A levels, a factor driving cilia disassembly and implicated in the pathogenesis of polycystic kidney disease." (PMID 40247090, 2025). "Aurora Kinase A (AURKA) promotes cell proliferation and is overexpressed in different types of polycystic kidney disease (PKD)." (PMID 38191531, 2024).
prostate intraepithelial neoplasia (2 papers, 2017 to 2024). A neoplastic proliferation of the epithelial cells that line the acini and the ducts of the prostate gland. "AURKA amplification has been detected in prostate intraepithelial neoplasia (PIN) lesions and may represent an early oncogenic event in PC." (PMID 38398199, 2024).
prostatic small cell neuroendocrine carcinoma (2 papers, 2021 to 2023). "It has been postulated that differentiated NE-like cells may progress to small-cell prostate carcinoma (SCPC) through the accumulation of additional genetic alterations, such as loss of RB1, MYCN, and AURKA amplification." (PMID 37740039, 2023).
Renal cyst (2 papers, 2023 to 2024). A fluid filled sac in the kidney. "Aberrant hyper-activation of AURKA correlates with the formation of renal cysts in ADPKD29 and JS15." (PMID 38191531, 2024). "Comparative analysis of these models and subsequent in vivo inhibition studies demonstrate that these effects are mediated, at least in part, by signalling through AKT which we show binds to AURKA in cystic kidneys." (PMID 38191531, 2024). "In ADPKD, signaling pathways activated in renal cysts by loss of PKD1 include many known to be activated and growth-promoting in cancer including WNT/CTNNB1, PI3K/AKT, mTOR/S6K, RAF/MEK/ERK, SRC, MYC, AURKA, and others." (PMID 37542051, 2023).
squamous cell carcinoma (2 papers, 2011 to 2022). A carcinoma arising from squamous epithelial cells. "Previous studies have found that the expression levels of AURKA in squamous cell carcinoma and adenocarcinoma are significantly different." (PMID 36247089, 2022).
Thrombocytopenia (2 papers, 2021 to 2025). A reduction in the number of circulating thrombocytes. "We therefore hypothesized that megakaryocyte progenitors in subsets of MDS patients with thrombocytopenia would elevate expression levels of mitotic genes, including AURKA, AURKB, and PLK1, which in turn would promote cytokinesis/cell cycling rather than endomitosis." (PMID 40813622, 2025).
thymoma (2 papers, 2021 to 2022). A neoplasm arising from the epithelial cells of the thymus. "Compared with that in corresponding normal tissues, the expression of AURKA mRNA was significantly increased in almost all tumors, except in thymoma." (PMID 35875069, 2022).
tongue cancer (2 papers, 2009 to 2022). A malignant neoplasm affecting the tongue. "Among them, AC099850.3 is the most co-expressed lncRNA, which is related to six differently expressed mRNAs, namely (CAV1, NRAS, ACSL3, AURKA, EIF2AK4 and RRM2), and its high expression level is closely related to the reduction in the survival rate of patients with tongue cancer." (PMID 35299954, 2022).
uterine cancer (2 papers, 2016 to 2021). Primary or metastatic malignant neoplasm involving the uterine corpus and/or the cervix. "The cox regression test outcomes indicated that increased expression of AURKA gene was associated with a poor prognosis in the bladder (BLCA), kidney (KIRC), liver (LIHC), lung (LUAD), prostate (PAAD), and uterine cancer (UCEC)." (PMID 34337875, 2021). "The results indicated that the expression level of AURKA gene in 13 common cancers increased significantly compared to normal samples or it survived poorly (HR >1, p < 0.01) in lung, prostate, kidney, bladder, and uterine cancers." (PMID 34337875, 2021).
acral melanomas (1 paper, 2017). "Alterations of RAS pathway members are also very frequent in acral melanomas, being detected in 87% of these patients: NRAS (17%), Aurora Kinase A (AURKA) (37.5%), Ciclin D1 (CCND1) or telomerase reverse transcriptase (TERT, 31%), and RAS (25%)." (PMID 29156643, 2017).
Alzheimer disease (1 paper, 2024). A progressive, neurodegenerative disease characterized by loss of function and death of nerve cells in several areas of the brain leading to loss of cognitive function such as memory and language. "Decreased activity of AURKA was found in Alzheimer’s disease (AD) brain samples, but little is known about the role of AURKA in AD pathogenesis." (PMID 38892390, 2024).
Azoospermia (1 paper, 2022). Absence of any measurable level of sperm,whereby spermatozoa cannot be observed even after centrifugation of the semen pellet. "Thus, the present study, in relation to the individual previous studies, aims to identify SPA17, PPP1R36, AURKA, TRIP13, PLK4, CCDC90B, and CCDC91 genes as important biomarkers of both teratozoospermia- and azoospermia-associated infertility in men." (PMID 36292606, 2022).
bone osteosarcoma (1 paper, 2022). A usually aggressive malignant bone-forming mesenchymal neoplasm arising from the bone. "Furthermore, p-Akt is phosphorylated by Aurora kinase A in human bone osteosarcoma epithelial cells (U2OS)." (PMID 35834029, 2022).
brain malformations (1 paper, 2020). "Recessive WDR62 mutations were identified in severe brain malformations, and the interaction between WDR62 and mitotic kinase AURKA is essential for drosophila brain growth." (PMID 32370292, 2020).
Burkitt lymphoma (1 paper, 2023). A rare form of malignant mature B-cell non-Hodgkin lymphoma. "Here, we report, for the first time, amplifications of aurora kinase genes (AURKA/B) in a patient with a history of periodontal abscess and the presence of a remaining nodule, diagnosed with Burkitt lymphoma and Epstein-Barr virus, and /HIV positive." (PMID 37436268, 2023). "Thus, MYCC rearrangements and higher expression of AURKA/B may be associated with therapy resistance, highlighting the importance of AURKA/B evaluation in Burkitt lymphoma." (PMID 37436268, 2023).
Cholecystitis (1 paper, 2019). The presence of inflammatory changes in the gallbladder. "As for multi-target inhibitors, Ilorasertib (ABT-348) targeting Aurora kinase A/B, VEGFR/PDGFR and Src family, and ENMD-2076 targeting Aurora kinase A, VEGFR2/FGFR/Flt-3/c-Kit, were found to cause more DLTs, such as pancreatic disease and hypertension, fatigue, cholecystitis, and QTc prolonged." (PMID 30642372, 2019).
clear cell sarcoma (1 paper, 2025). A rare malignant neoplasm with melanocytic differentiation characterized by the presence of polygonal or spindle shaped clear cells. "have shown that in clear cell sarcoma, the expression of the EWS‐ATF1 fusion gene led to increased levels of AURKA and PLK1." (PMID 39789853, 2025).
colon adenocarcinoma (1 paper, 2025).
colorectal polyp (1 paper, 2018). "For instance, the increased copy number of AURKA is associated with the evolution of colorectal polyp into carcinoma." (PMID 30070631, 2018).
dengue (1 paper, 2025). "While several genes consistently identified dysregulated in dengue patients, such as CXCL10, ZWINT, BUB1, AURKA, STAT1, etc. there was a notable variability in gene expression patterns across the datasets." (PMID 40100920, 2025). "Key regulatory genes such as AURKA, BUB1, BUB3, and CDK1 are found to be involved in cell cycle regulation and have roles in immune-related pathways, underscoring their importance in the host immune response to Dengue virus infection." (PMID 40100920, 2025).
Duchenne muscular dystrophy (1 paper, 2022). Duchenne muscular dystrophy (DMD) is a neuromuscular disease characterized by rapidly progressive muscle weakness and wasting due to degeneration of skeletal, smooth and cardiac muscle. "In particular, human WJ-MSCs with high expression of AURKA might have therapeutic efficacy against muscle diseases, such as Duchenne muscular dystrophy (DMD)." (PMID 35450345, 2022).